IL6 (interleukin 6)
Diseases named in the same sentence as IL6 in open-access papers (continued):
Sharing a sentence is not in itself a finding about the gene and the disease.
tumor (continued). "In HPV associated tumor cells, STAT3 expression may be indirectly activated by NFκB, since IL-6 is a transcription target of the later and known activator of the STAT3 pathway." (PMID 33330068, 2020). "IL-6 plays an important role in the tumor-related systemic inflammatory response, not only as a major inducer of CRP but also as a direct inducer of anti-inflammatory molecules, which are also considered potential mechanisms by which IL-6 participates in the occurrence of irAEs." (PMID 33317597, 2020). "Serum IL-6 also acts as an attractant for tumor cells, facilitating migration." (PMID 33076397, 2020). "Our data therefore are consistent with results described by Karakasheva and colleagues, making it likely that the enhanced IL‐6 expression in our fibroblasts is not only part of a fibroblast activation programme but also a reciprocal signal to the tumour cells to enhance their growth." (PMID 32133790, 2020). "IL-6 is secreted by a variety of cells, like keratinocyte, endothelial cells, neural cells, lymphocytes, and bone cells, when stimulated by specific inducers; however, constitutive expression triggers tumor formation." (PMID 31979357, 2020). "In our studies, MSCs-IL10 exhibited a strong inhibitory effect on the growth of PANC-1 subcutaneous tumors, and can well inhibited secretion of TNF-α and IL6, the pro-inflammatory cytokines and tumor angiogenesis, so that tumor-bearing mice had longer survival." (PMID 32742480, 2020). "IL-6 production within the tumor microenvironment could directly contribute to poorer outcomes in patients with cancer." (PMID 33330085, 2020). "As IL-6 is secreted in both AN-exposed fibroblasts and epithelial cells, its blockade could prevent tumor microenvironment, which is required for malignant transformation of epithelial cells and fibroblasts." (PMID 32856877, 2020). "Moreover, under the influence of IL-6, the concentration of EpCam+CD44hiCD24low tumor stem cells increased dramatically (2.5 times), and the EpCam+CD44lowCD24– concentration decreased two-fold." (PMID 32523653, 2020). "It suggests that pretreating macrophages with PP VII before their transformation promotes the proliferation-inhibiting effect of IFN-γ transformed macrophage CM on tumor cells, while inhibited the proliferation-promoting effect of IL-6-transformed macrophages CM." (PMID 33288772, 2020). "Moreover, the tumor microenvironment is engulfed of immune suppressive cytokines such as IL-6 and IL-10 as well as T-regulatory cells whose migration nearby tumor cells contribute to enhance the evasion from the immune system control." (PMID 32751327, 2020). "Recently, we demonstrated that the chr8p gene SH2D4A (Src homology 2 domain-containing 4A) exhibits tumor-suppressive functions in vivo and in vitro by inhibiting the Interleukin-6 (IL-6) induced Signal Transducer and Activator of Transcription 3 (STAT3) signaling pathway in HCC5,6." (PMID 33257655, 2020). "Notably, there is also growing evidence that there is a cross-talk between tumor-associated macrophages and MDSC via secretion of IL-6, which leads to the increased negative regulatory activity of MDSCs and T regs in tumor stroma." (PMID 35582227, 2020). "In details, in all the analyzed patients and independently from the tumor site of origin, the levels of IL-6 increased after 10 days of treatment with lanreotide and decreased in the following six months; whereas the levels of IL-2 and IL-10 raised only in some patients." (PMID 32766136, 2020). "Moreover, we have shown in our previous studies that IL-1β and IL-6 are up-regulated in NPC cells by LMP1-induced glycolysis or suppression of STING signals, leading to tumor-associated MDSC expansion." (PMID 32632113, 2020). "IL6 is produced by tumor cells themselves and diverse cell types in the TME, such as cancer-associated fibroblasts (CAFs) and tumor-associated macrophages (TAMs), both of which have been reported to promote cancer stem cell properties through paracrine IL6 34,35." (PMID 32308766, 2020).
tumor (continued). "IL-6 caused a 2.3-fold increase in the EpCam+CD44lowCD24– and 2-fold decrease in the EpCam+CD44hiCD24–/low subpopulations of tumor stem cells with no induction of mammospheres." (PMID 32523653, 2020). "Extracellular S100A4 in the TME induces the release of pro-inflammatory factors (e.g., interleukin 6 (IL-6), interleukin 8 (IL-8), and C-X-C motif chemokine 10 (CXCL10)), which then converts monocytes into tumour-associated macrophages (TAMs), resulting in metastasis and drug resistance." (PMID 32722137, 2020). "A recent murine study suggested that IL-6 may induce either pro- or anti-inflammatory actions depending on cell source, potentially explaining the beneficial, suppressive effects on tumor growth and immunomodulatory actions of muscle derived IL-6." (PMID 33329046, 2020). "In addition, the levels of IL-6 are increased in sarcopenic patients which can contribute to tumor growth and alters the function of immune cells including T-cell subsets." (PMID 33194687, 2020). "Moreover, IL‐6 can act on numerous cell types within the tumor microenvironment to sustain a pro‐tumoral milieu by supporting angiogenesis and tumor evasion of immune surveillance." (PMID 31608444, 2020). "Furthermore, exercise post-treatment reduced tumor volume and the pro-inflammatory cytokine IL-6 in addition to restoring muscle mass." (PMID 33233839, 2020). "These assays indicated that the effect of Faecalibacterium prausnitzii on JAK2/STAT3 was mediated at least in part by IL-6 and the anti-tumor effect of Faecalibacterium prausnitzii may be through inhibition of the IL6/STAT3 pathway." (PMID 32272885, 2020). "Moreover, neutrophils and macrophages have been reported to secrete tumor growth-promoting factors, IL-6, IL-8, including vascular endothelial growth factor, and elastases, and thus likely contribute to a pro-tumor microenvironment." (PMID 33287745, 2020). "Furthermore, iCAFs have been widely proved to promote tumor progression by secreting chemokines and cytokines such as IL-6 and CXCL12." (PMID 33292666, 2020). "Furthermore, both results of immunohistochemistry staining and Western blot showed that elevated protein expressions of COX-2, IL-6, β-catenin, and snail were also detected in the tumor cells of AOM/DSS-treated mice, and these increases were prevented by PL." (PMID 33343354, 2020). "Furthermore, studies have shown that TIM-3 is involved in M2 polarization in both TGF-β-dependent and -independent manners and promotes tumor growth through the NF-κB/IL-6 axis." (PMID 33425759, 2020). "Concomitantly, the tumor burden of WT mice was also greater than that of IL-6 KO mice." (PMID 32867390, 2020). "IL-6 plays a critical role in the expansion and differentiation of tumor cells and can also modulate the tumor’s therapeutic resistance, such as multidrug resistance (MDR), whose engagement triggers the activation of JAK and the downstream effectors STAT3, SHP-2/Ras, and PI3K/Akt." (PMID 32847008, 2020). "Moreover, CAFs secrete pro-inflammatory cytokines, such as IL-6 and IL-8 to promote tumor progression." (PMID 32139701, 2020). "Also, a positive correlation was observed between increased cytokine expression (especially IL-6) by tumor cells and activation and redistribution of Natural Killer cells, which in turn is directly responsible for suppressing tumor growth by up to 60%." (PMID 33613297, 2020). "The reduced levels of tumour‐derived IL‐6 in circulation could thus, to an unknown extent, be a result of reduced number of IL‐6‐producing TOV21G cells." (PMID 31436048, 2020).
tumor (continued). "Furthermore, IL-6 and TNFα are highly expressed in the malignant tumor microenvironment, which can promote tumor invasion, distant tumor metastasis, angiogenesis, and tumor resistance." (PMID 32317968, 2020). "A hypothesis is that tumor production of IL-6 promotes megakaryopoiesis via hepatic TPO, leading to thrombocytosis." (PMID 33365273, 2020). "In colorectal cancer, IL-6 was shown to stimulate IL-10 production by tumor cells." (PMID 33042814, 2020). "Indeed, IL-10 and/or IL-6 signaling in ABC-DLBCL tumors regulate the malignant cell and tumor microenvironment, suggesting that suppression of IL-10 and IL-6 secretion is beneficial for treating ABC-DLBCL." (PMID 32391356, 2020). "IL‐6 levels were also elevated in serum of a subgroup of EwS patients with poor prognosis and constitute an indicator of poor overall survival and event‐free survival in STS, suggesting a possible association with aggressive tumor behavior." (PMID 33047515, 2020). "IL-6 stimulates cancer growth, metastasis and immune evasion in several tumor types." (PMID 33194755, 2020). "Several crucial CRS processes involve macrophages, including the initial activation of macrophages by the CD40L-CD40 interaction in the CAR T cell-tumor environment, the secretion of core cytokines (IL-6, IL-1 and IFN-γ) in CRS and a catecholamine self-amplification loop in macrophages." (PMID 32665874, 2020). "Adding IL-6 and VEGF into culture medium could reverse the ability of At-EE inhibiting angiogenesis, which confirmed At-EE restrained angiogenesis through decreasing tumor cell-secreted IL-6 and VEGF." (PMID 32190078, 2020). "In particular, mast cells play a role in tumor initiation, maintenance, and growth by synthesizing and secreting matrix metalloproteinases, various cytokines (IL6 and TNFα), and multiple mitogens [vascular endothelial growth factor precursor (VEGF) and platelet-derived growth factor (PDGF)]." (PMID 33244317, 2020). "In addition, endostatin can reduce the expression levels of VEGF, TGF-β, IL-6, and IL-17 in tumor tissues, increase the expression levels of IFN-γ and HIF-1α, suppressing growth and angiogenesis of tumors." (PMID 33224886, 2020). "Collectively, HJ901 treatment may have reduced IL-6 and IL-10 secretion in cells and suppressed cell proliferation and tumor growth in cells and mice through possible mechanisms that modulate the TLR7/9, NF-κB, and JAK2-STAT3 signaling pathways." (PMID 32391356, 2020). "Finally, tumor cells produce Csf1 and IL-34 which recruit immunosuppressive Csf1r+ TAMs that produce IL-6, IL-10, and TGFβ, all factors that promote a cycle of immune suppression." (PMID 33584701, 2020). "High levels of IL-6 are related to tumor aggressiveness and poor response to therapies." (PMID 32326073, 2020). "A study conducted on CSCs derived from OSCC cell lines SAS and OECM-1 as well as a normal human gingival epithelioid cell line aimed to explore the cytotoxic effect of immune-modulatory proteins on OCSCs reported a tumor-suppressive effect via inhibition of the IL-6/STAT3 signaling pathway." (PMID 33003438, 2020). "In animal studies, the use of IL-6 signaling inhibitors reduced tumor growth in PDAC37." (PMID 33230218, 2020). "IL-6 promotes tumor cell proliferation by acting through the STAT3 pathway to upregulate Myc expression and induces the expression of anti-apoptotic genes encoding bcl2, bcl-XL and survivin to promote tumor survival." (PMID 33076397, 2020). "In PD, increased cytokine levels in response to cellular stress can lead to neuronal cell death whereas in GBM, cytokines like interleukins IL-1β, IL-6, and IL-8 released by the tumor cells, inhibit the immune response and allow the tumor cells to escape the eradication by the immune system." (PMID 32973662, 2020). "In addition, overexpression of IL-6 from MSCs has been correlated with the enhanced expression of ICAM-I in tumor stromal cells resulting in the invasive potential of cancer cells to increase." (PMID 32717819, 2020).
tumor (continued). "Notably, adding anti-IL6 or anti-IL1β neutralizing antibodies to the co-culture system for the purpose of interrupting the tumor-neuroglia interaction significantly inhibited the development of lung metastasis." (PMID 32308766, 2020). "IL-6, an inflammatory cytokine, promotes cell metastasis in tumor." (PMID 32201528, 2020). "IL6 also works on other cells within the tumor stroma, promoting angiogenesis and tumor evasion." (PMID 33381115, 2020). "Thus, collectively, IL-6/JAK/STAT3 pathway contributes to the development of a highly immunosuppressive tumor microenvironment." (PMID 32824865, 2020). "Whilst there is little information on its anti-tumour immunomodulatory effects, studies have shown that C3G reduced rheumatoid arthritis presentation, and concurrently increased IL-10, Tregs, and decreased IL-6, IFN-γ and NK cell activity." (PMID 32183059, 2020). "IL-6 promotes tumor growth by activating STAT3 in intestinal epithelial cells." (PMID 33291412, 2020). "Accordingly, administering an inhibitor of CXCR4, the receptor for CXCL12, to the PDA-bearing mice led to the rapid accumulation of effector T cells within the tumor and blockage IL-6 could improve T-cell trafficking, migration and tumor immunosuppression." (PMID 33613544, 2020). "Once activated, this transcription factor regulated expression of cytokines and factors involved in cancer development and progression such as IL-6 for tumor cell survival, angiogenic factors VEGF and IL-8, along with further production of inflammatory mediators for immune cell recruitment." (PMID 33076397, 2020). "In particular, we would suggest that well-vascularised tumours, with low IL-6, might be most responsive to its dual anti-angiogenic and anti-CSC activity, although this will need to be further validated in fresh clinical samples." (PMID 31772325, 2020). "In addition to direct effects on tumor cells, IL-6/JAK/STAT3 signaling has a fundamental effect on tumor-infiltrating immune cells." (PMID 32824865, 2020). "Moreover, detection of inflammatory cytokines showed that Kejinyan decoction downregulated TNF-α, IFN-γ, IL-6, as well as IL-4, IL-13 in tumor microenvironment." (PMID 32943999, 2020). "In particular, tumor cells can promote fibrinogen secretion by producing interleukin-6." (PMID 33376559, 2020). "IL-6 can induce tumorigenesis through the hypermethylation of tumor suppressor genes." (PMID 32283655, 2020). "Various previous researches provided a rational explanation that the levels of epidermal growth factor receptor amplification and interleukin 6 could be upregulated by TERT promoter mutations, inducing tumor angiogenesis and necrosis." (PMID 32509858, 2020). "A high RDW may be driven by the excessive production of cytokines in the tumour microenvironment, such as IL-6 and TNF-a." (PMID 32705478, 2020). "The high dose IR of tumor cells also effectively reduced their production of IL-6 and RANTES." (PMID 32117702, 2020). "In addition, DOX increases circulating IL-6 levels; however, physical exercise can reduce the transcription of IL-6 in the tumor." (PMID 33233839, 2020). "Notably, inhibition of CCL2 alone or in combination with anti-IL-6 therapy markedly reduced metastases and increased survival of the tumor-bearing animals." (PMID 31811337, 2020). "There is a reciprocal interplay between CAFs and tumor cells, wherein tumor cells secrete IL6 and promotes CAFs to secrete matrix metalloproteases (MMPs) which in turn remodels the ECM, and further induces secretion of IL6 from tumor cells, thereby driving EMT." (PMID 32754615, 2020). "At the molecular biology level, the malignant grade of tumor is associated with the levels of platelets and cytokines, for example, the VEGF, platelet-derived growth factor (PDGF), transforming growth factor β (TGF-β), and interleukin 6 (IL-6)." (PMID 33243184, 2020).
tumor (continued). "Genes associated with DNA methylation mediated transcriptional silencing were up-regulated in tumor invasive I-MDSCs and involved in cell transport and immunosuppression signaling pathways, including Wnt, IL-6, and mitogen-activated protein kinase (MAPK) signaling in I-MDSCs." (PMID 33027968, 2020). "Also, it was shown that the presence of the HPV was associated with increased inflammatory cytokines (IL-1, IL-6, IL-17, TGF-β, TNF-α, and NF-kB) and tumor progression." (PMID 32458652, 2020). "Similarly, NF-κB activation in CAFs by EV-derived miR-1247-3p in metastatic hepatocellular carcinoma (HCC) leads to a tumor-promoting secretion of IL-6 and IL-8." (PMID 33553157, 2020). "The elevated levels of IL-6 in the OC patients observed in our studies may therefore contribute to tumor progression and impede immunotherapy." (PMID 33062717, 2020). "Combination of anti-IL-6 plus anti-PD-L1 reduced tumor growth and prolonged mouse survival." (PMID 33584701, 2020). "For instance, tumour cells often secrete IL-6 and macrophage colony-stimulating factor, which may shift the differentiation of monocytes towards macrophages rather than DCs." (PMID 32565898, 2020). "Previous studies have shown that IL-6 from immune system cells can promote the expression of miR-21 and miR-29b in tumor cells which promotes their invasiveness ability; thus, as tumor cells stimulate IL-6 expression in immune cells they can promote their own tumor progression." (PMID 32927431, 2020). "Indeed, ELISA results indicated that the expression of serum TNFα, IL-12 and IL-6, which are functional markers of M1 macrophages, significantly increased in V&miR-99b-treated or V&miR-125a-treated tumor-bearing mice." (PMID 32948650, 2020). "Although IL-6 is a key mediator of tumour-associated inflammation, IL-6 was not a stronger prognostic factor than IL-8 in multivariable analysis." (PMID 32488137, 2020). "It poses an issue that specific adipokines such as polyfunctional IL-6 could be released by different cell types, primary adipocytes, immune cells, or tumor cells." (PMID 32787888, 2020). "Although in physiological conditions neutrophils and macrophages are essential for the elimination of necrotic cells and wound repair, excess of these cells favors tumor development through activation of the IL‐6/Stat3 signaling pathway, which promotes cellular proliferation." (PMID 33326125, 2020). "Thus, CAFs expressing high levels of αSMA (myoCAF phenotype) are in proximity to neoplastic cells, while CAFs expressing higher levels of IL-6 (iCAFs phenotype) are more distantly distributed inside the tumor." (PMID 32781778, 2020). "The Th17 response can thus promote tumor growth, in part via an IL-6-Stat3 pathway." (PMID 32560326, 2020). "An ELISA was performed to verify the IL-6 levels in the sera of the tumor-bearing mice." (PMID 32565805, 2020). "Indeed, tumor-derived sEVs can stimulate a significant release of various cytokines, including IL-6, TNF, and TGF-β by CD14+ monocytes from healthy donors and can promote suppression of their functions as well as the proliferation of T cells." (PMID 32015297, 2020). "Several studies point to tumour‐derived interleukin 6 (IL‐6) as a central driver of cachexia." (PMID 31436048, 2020). "Other studies demonstrated, that knockout of gp130, a transmembrane protein involved in the signal-transduction of IL-6 and other cytokines, prevented the development of neuropathic pain in animal models of mechanical nerve injury, tumor pain, and inflammation." (PMID 31969555, 2020). "Several cytokines, which can arise from either tumor cells or immunocytes, such as tumor necrosis factor (TNF)-α, interleukin (IL)-1β, IL-6, IL-8, IL-10, and vascular endothelial growth factor (VEGF), have been linked with cancers and can either promote or inhibit tumor development." (PMID 32847533, 2020).